RNU6-984P (RNA, U6 small nuclear 984, pseudogene)
Gene: Small nuclear RNA gene on chromosome 9 (109,196,201 to 109,196,309, reverse strand). Ensembl gene ENSG00000200106.
Homologues: Orthologues: chimpanzee U6 (97% identical), macaque U6 (90% identical), pig U6 (88% identical), guinea pig U6 (83% identical), rat U6 (79% identical). Paralogues in human: RNU6-35P (90% identical), RNU6-16P (87% identical), RNU6-211P (87% identical), RNU6-25P (87% identical), RNU6-378P (87% identical), RNU6-820P (87% identical), RNU6-1 (86% identical), RNU6-1152P (86% identical), RNU6-11P (86% identical), RNU6-15P (86% identical), RNU6-188P (86% identical), RNU6-19P (86% identical), and 1287 more.